PITX3 (paired like homeodomain 3)
Description:
Transcriptional regulator which is important for the differentiation and maintenance of meso-diencephalic dopaminergic (mdDA) neurons during development. In addition to its importance during development, it also has roles in the long-term survival and maintenance of the mdDA neurons. Activates NR4A2/NURR1-mediated transcription of genes such as SLC6A3, SLC18A2, TH and DRD2 which are essential for development of mdDA neurons. Acts by decreasing the interaction of NR4A2/NURR1 with the corepressor NCOR2/SMRT which acts through histone deacetylases (HDACs) to keep promoters of NR4A2/NURR1 target genes in a repressed deacetylated state. Essential for the normal lens development and differentiation. Plays a critical role in the maintenance of mitotic activity of lens epithelial cells, fiber cell differentiation and in the control of the temporal and spatial activation of fiber cell-specific crystallins. Positively regulates FOXE3 expression and negatively regulates PROX1 in the anterior lens epithelium, preventing activation of CDKN1B/P27Kip1 and CDKN1C/P57Kip2 and thus maintains lens epithelial cells in cell cycle (By similarity).
Synonyms: ASGD1; ASMD; ASOD; CTPP4; CTRCT11
Tractability: No criterion of Open Targets' tractability assessment is met for any kind of drug.
Gene: Protein-coding gene on chromosome 10 (102,230,189 to 102,241,512, reverse strand). Ensembl gene ENSG00000107859.
Subcellular location: Nucleus
Gene Ontology:
Molecular function: sequence-specific double-stranded DNA binding; DNA-binding transcription factor activity, RNA polymerase II-specific; RNA polymerase II cis-regulatory region sequence-specific DNA binding; DNA binding; DNA-binding transcription factor activity
Biological process: anatomical structure morphogenesis; animal organ morphogenesis; dopaminergic neuron differentiation; lens development in camera-type eye; lens morphogenesis in camera-type eye; midbrain development; positive regulation of DNA-templated transcription; regulation of DNA-templated transcription; regulation of transcription by RNA polymerase II; cellular response to glial cell derived neurotrophic factor; negative regulation of gliogenesis; negative regulation of neurogenesis; positive regulation of cell proliferation in midbrain; positive regulation of neuron apoptotic process; response to cocaine; response to immobilization stress; response to methamphetamine hydrochloride
Cellular component: chromatin; nucleus
Genetic constraint (gnomAD): Loss-of-function variants: 3 observed, 11.23 expected, observed/expected ratio (o/e) 0.27, 90% interval 0.12 to 0.69. The upper end of that interval is the gene's LOEUF score, 0.69, which puts it in group 2 of 6, group 1 being the genes least tolerant of losing a copy. Missense variants: 358 observed, 393.75 expected, observed/expected ratio (o/e) 0.91, 90% interval 0.83 to 0.99. Synonymous variants: 194 observed, 192.83 expected, observed/expected ratio (o/e) 1.01, 90% interval 0.89 to 1.13.
Homologues: Orthologues: chimpanzee PITX3 (100% identical), macaque PITX3 (99% identical), rabbit PITX3 (99% identical), dog PITX3 (99% identical), mouse Pitx3 (98% identical), rat Pitx3 (98% identical), pig PITX3 (97% identical), guinea pig PITX3 (92% identical). Paralogues in human: PITX2 (58% identical), PITX1 (55% identical), ARX (29% identical), DMBX1 (27% identical), DRGX (26% identical), PAX7 (26% identical), PAX3 (25% identical), ALX4 (25% identical), VSX2 (25% identical), SHOX (24% identical), SHOX2 (24% identical), RAX (23% identical), and 38 more.
Diseases named in the same sentence as PITX3 in open-access papers:
PITX3 is named in the same sentence as 52 diseases in open-access papers, as found by Europe PMC text mining. Sharing a sentence is not in itself a finding about the gene and the disease. The quoted sentences say what the papers report.
aphakia (20 papers, 2006 to 2023). "A case in point is aphakia mice, which have a spontaneous mutation in the Pitx3 transcription factor gene, that results in selective developmental loss of nigrostriatal dopamine neurons and an ~90% reduction in dorsal striatal dopamine." (PMID 32973447, 2020). "Another spontaneous Pitx3 mutant line (gene symbol miak—microphthalmia and aphakia) has a nonsense mutation (Tyr148X) leading to a truncation of PITX3 lacking the OAR domain; its phenotype is quite similar to ak and eyl." (PMID 30919050, 2019). "The so called aphakia mice lack the expression of Pitx3 due to a homozygote mutation in the Pitx3-gene resulting in a selective degeneration of mesencephalic dopaminergic neurons during embryonic development." (PMID 28883785, 2017). "In the present study, we report that a novel nonsense mutation located outside the homeodomain in Pitx3 causes microphthalmia and aphakia in miak mice." (PMID 25347445, 2014). "By positional cloning, we identified the nonsense mutation c.444C>A outside the genomic region that encodes the homeodomain of the paired-like homeodomain transcription factor 3 gene (Pitx3) as the mutation responsible for the microphthalmia and aphakia." (PMID 25347445, 2014). "We identified a nonsense mutation, c.444C>A of Pitx3, which leads to p.148Tyr>X, and predicted that this mutation is a strong candidate to explain the microphthalmia and aphakia in the miak mutant." (PMID 25347445, 2014). "Analysis of a Pitx3-deficient mouse called aphakia (ak) has provided evidence that DA neurons react differentially to the ablation of Pitx3 during development, indicating that specific vulnerability of mdDA subsets exist already during development." (PMID 24116087, 2013). "In the aphakia mouse mutant, two deletions in the promoter of the homeobox transcription factor Pitx3 lead to loss of its function and to arrest of eye development at the lens stalk stage." (PMID 21633712, 2011). "A similar phenotype is also the key feature in the Pitx3 loss of function aphakia mouse, where the lens begins to form, but its development is abnormal." (PMID 20084168, 2010). "Pitx3 is expressed in the lens vesicle and is later limited to lens epithelium, and Pitx3 deletion causes apoptosis, abnormal lens fiber differentiation, and loss of the lens (aphakia)." (PMID 30295986, 2018). "However, the Pitx3-mutation in aphakia mice remains the locus coeruleus intact, thus alterations of hippocampal neurogenesis in aphakia mice are independent of the noradrenergic system." (PMID 28883785, 2017). "Interestingly, heterozygous aphakia mice with reduced PITX3 expression showed increased DA neuron loss in the SNpc after MPTP treatment." (PMID 25565977, 2014). "The same is true in a Pitx3 mutant aphakia (allele symbol ak; )." (PMID 19102749, 2008). "Therefore, we speculated that the microphthalmos/aphakia in this mutant is caused by the expression of truncated PITX3, resulting in the abnormal expression of downstream targets and lens fiber proteins." (PMID 25347445, 2014). "Pitx3−/− or aphakia mice represent a genetic model of PD, in which most of the dopaminergic neurons from the substantia nigra do not develop properly." (PMID 37887070, 2023). "Although Pitx3 is expressed in both SN and VTA neurons, the Pitx3-deficient aphakia mouse mutant shows a selective loss of DA neurons only in the SN." (PMID 32503161, 2020). "In mice, Pitx3 is expressed in the lens, and homozygous mouse mutants with lenticular expression of truncated Pitx3 presented with microphthalmia and aphakia." (PMID 33425902, 2020). "Here we examined adult hippocampal neurogenesis in the Pitx3-mutant mouse model of PD (aphakia mice), which phenotypically shows a selective embryonic degeneration of dopamine neurons within the SN and to a smaller extent in the ventral tegmental area (VTA)." (PMID 28883785, 2017).
aphakia (continued). "The mouse Pitx3 gene was shown to be involved in aphakia, a recessive mutant phenotype characterized by small eyes lacking the lens." (PMID 17888164, 2007). "PITX3 has been reported to be mapped close to aphakia on mouse chromosome 19." (PMID 36153513, 2022). "In aphakia mice, two major deletions in the Pitx3 promoter are responsible for this defect." (PMID 30991053, 2019). "Since a mutation in the Pitx3 gene is causative for the absence of the lens vesicle in the aphakia mutant, we checked its expression in the Aey69 mutant." (PMID 30991053, 2019). "Microphthalmos or aphakia could be detected in mice with knockdown of Pitx3." (PMID 36153513, 2022). "Deletions within the Pitx3 promoter region in mice produce the aphakia phenotype, which is characterized by small eyes lacking a lens." (PMID 21698120, 2011).
Parkinson disease (19 papers, 2010 to 2025). A progressive degenerative disorder of the central nervous system characterized by loss of dopamine producing neurons in the substantia nigra and the presence of Lewy bodies in the substantia nigra and locus coeruleus. "Mice with a homozygous deletion of Pitx3 exhibit a significant loss of midbrain dopamine neurons and reduced striatal dopamine innervation, resembling a Parkinson’s-like condition." (PMID 39456033, 2024). "In a Pitx3-deficient mouse model, which mimics the loss of dopaminergic neurons seen in Parkinson’s disease, Ser40 phosphorylation remained manipulable despite reduced tyrosine hydroxylase protein levels." (PMID 39456033, 2024). "The mutation in PITX3 is associated with abnormal development of the anterior eye, especially the lens and its polymorphism is related to Parkinson's disease, dementia, and neurological abnormalities." (PMID 37139083, 2023). "PITX3 expression is seen in the developing lens, skeletal muscle, and dopaminergic neurons of the substantia nigra in the brain and the PITX3 polymorphisms have been shown to be associated with Parkinson disease dementia and with neurological abnormalities." (PMID 34345029, 2022). "For example, a novel synonymous SNP in the PITX3 gene may enhance Parkinson’s disease risk among individuals of Chinese ethnicity." (PMID 40612150, 2025). "Although many studies have shown the link between PITX3 and Parkinson’s disease, the clear association with TS is largely unknown." (PMID 37187752, 2023). "Recently PITX3 polymorphisms have been shown to be associated with Parkinson disease." (PMID 21633712, 2011). "In addition, mice homozygous for the eyl allele of Pitx3 exhibit symptoms like Parkinson’s disease in humans." (PMID 21042563, 2010). "Recently, variations in CRYAB and PITX3 have been associated with increased susceptibility to multiple sclerosis and Parkinson’s disease, respectively, raising awareness about the possibility of acquired neurodegenerative conditions in certain patients with early-onset cataract." (PMID 21042563, 2010). "Using a Pitx3 conditional knockout it was demonstrated that Pitx3 deficiency in fully differentiated mdDA neurons results in a rapid reduction in striatal dopamine levels, behavioral abnormalities, and progressive neuronal loss resembling the symptoms of Parkinson’s disease." (PMID 40169558, 2025). "The PITX3 deficiency can lead to the loss of the substantia nigra striatum path, the deprivation of dopaminergic neurons in the substantia nigra, and the impairment of dopaminergic development, which may drive the development of Parkinson’s disease." (PMID 37187752, 2023). "The paired-like homeodomain transcription factor 3 (PITX3), located on chromosome 10q24, plays an important role in the midbrain dopamine system development, and single-nucleotide polymorphisms within the PITX3 gene have been associated with Parkinson’s disease." (PMID 28174607, 2017). "Pitx3 is essential for the survival of dopaminergic neurons of the substantia nigra, a key cellular substrate of Parkinson's disease." (PMID 39190555, 2024). "In Parkinson’s disease (PD) animals, it has been shown that lncRNA Xist/miR-133b-3p/Pitx3 axis protect dopaminergic neurons through activation of CB2R with AM1241, which alleviates PD." (PMID 34178980, 2021). "Since Pitx3 is also expressed in the substantia nigra of the brain, this mutation affects also the formation of dopaminergic neurons in the substantia nigra; Pitx3 mouse mutant lines are, therefore, an excellent model for Parkinson’s disease." (PMID 30919050, 2019). "In addition, dlk1 is involved in neuronal differentiation and Parkinson’s disease pathology along with other genes such as Nurr1 and Pitx3." (PMID 38051734, 2023). "PITX3 is involved in transcription of a micro-RNA that is known to have reduced expression levels in Parkinson’s diseased brains and may also contribute to the Alzheimer’s pathology development." (PMID 24363376, 2014).
Parkinson disease (continued). "As a model of Parkinson’s disease (PD), ASCL1, PITX3, NURR1, and LMX1A-induced dopaminergic neurons show α-synuclein accumulation as seen in PD, offering a physiologically relevant in vitro model of the ageing brain." (PMID 41301876, 2025).
cataract (18 papers, 2007 to 2024). Partial or complete opacity of the crystalline lens of one or both eyes that decreases visual acuity and eventually results in blindness. "It has been reported that most of the cataracts caused by PITX3 mutation are posterior polar cataracts, sometimes accompanied with ASMD." (PMID 37139083, 2023). "So far, 14 studies have reported 11 unique PITX3 mutations that can cause congenital cataracts, including congenital or early childhood cataracts, ASMD, corneal opacity, microphthalmia, microcornea, nystagmus, glaucoma, and other eye defects." (PMID 37139083, 2023). "For these affected individuals with heterozygous variants, cataracts were the most common manifestations and were detected in 92.74% of patients with PITX3 variants." (PMID 36153513, 2022). "The mutation of Pitx3 and Foxe3 genes can cause the mesenchymal dysgenesis of anterior segment and cataracts in humans, and the knockdown of Pitx3 and Foxe3 in zebrafish via antisense morpholino results in the lens dysmorphogenesis." (PMID 34451814, 2021). "A point mutation (p.13Ser>Arg) and a truncation by frameshift mutation (p.Gly220ProfsX94) in PITX3 cause dominant cataracts and ASMD, respectively, in humans." (PMID 25347445, 2014). "The transcription factor Pitx3 is critical for lens development and formation, and previous studies have revealed that mutations in PITX3 are associated with cataracts." (PMID 23776437, 2013). "For example, paired-like homeodomain transcription factors 2 and 3 (PITX2, PITX3) have been implicated in Axenfeld-Rieger syndrome and cataracts, respectively." (PMID 22539872, 2012). "Mutations in the homologus human PITX3 gene have been demonstrated to cause cataracts and anterior segment dysgenesis." (PMID 21633712, 2011). "PITX3 deficiency results in a spectrum of phenotypes from isolated cataracts to microphthalmia in humans, and lens degeneration in mice and zebrafish." (PMID 21698120, 2011). "In fact, the mutation in PITX3, a transcription factor containing a homeodomain, has been demonstrated to cause cataracts and anterior segment mesenchymal dysgenesis in several families from different ethnic origins." (PMID 20376326, 2010). "Some of the congenital cataracts stem from mutations of transcription factors such as Pax6, Pitx3, Eya and others." (PMID 19936087, 2007). "Human patients with point mutations in PITX3 demonstrate congenital cataracts along with anterior segment defects in some cases when one allele is affected and microphthalmia with brain malformations when both copies are mutated." (PMID 17888164, 2007). "PITX3: A highly recurrent duplication mutation (c.640_656dup17bp) in the human gene for paired-like homeodomain transcription factor 3 (PITX3) on chromosome 10q was first discovered in families with autosomal dominant cataract and anterior segment mesenchymal dysgenesis (ASMD)." (PMID 38927721, 2024). "The PITX3-S13N (N-terminal) mutation was identified in a family with autosomal-dominant congenital total cataract while the recurrent C-terminal mutation, PITX3-G219fs, was found in multiple pedigrees affected with dominant forms of cataracts often accompanied by severe anterior segment dysgenesis." (PMID 17888164, 2007). "In humans, PITX3 mutations were first reported to play a role in dominant anterior segment mesenchymal dysgenesis (ASMD) and cataracts." (PMID 25347445, 2014). "Mutations in both PITX3 and MIP/AQP0 are implicated in congenital cataracts in humans and result in lens phenotypes in mice." (PMID 21698120, 2011). "Unlike other transcription factors that cause ASMD, PITX3 gene mutations can lead to solitary cataracts with or without ASMD (postpolar cataract is the main feature)." (PMID 37139083, 2023). "Although the role of the four studied genes: PAX6, PITX3, HSF4 and LIM2 in both ocular and central nervous system development, we report the absence of mutations in all studied genes in four families with phenotypes associating cataract, MR and microcephaly." (PMID 22103961, 2011).
cataract (continued). "As for PITX3, which is linked primarily with cataracts with or without anterior segment defects, our findings suggest that it is not a major cause of congenital cataract." (PMID 20806047, 2010). "Therefore, our data suggest that PITX3 is involved in direct regulation of MIP/AQP0 expression and that the alteration of MIP/AQP0 expression is likely to contribute to the lens phenotype in cataract patients with PITX3 mutations." (PMID 21698120, 2011).
congenital cataracts (15 papers, 2008 to 2024). "PITX2 variants cause Axenfeld–Rieger syndrome, a disorder that affects primarily the eyes, whereas PITX3 variants are associated with congenital cataracts." (PMID 39190555, 2024). "PITX3 has been reported to be associated with congenital cataracts, anterior segment mesenchymal dysgenesis, Peters’ anomaly, and microphthalmia." (PMID 36153513, 2022). "Human patients with point mutations in PITX3 demonstrate congenital cataracts along with anterior segment defects (ASD) in some cases when one allele is affected and microphthalmia with brain malformations when both copies are mutated." (PMID 20084168, 2010). "In the current study, a family with autosomal recessive congenital cataract (ARCC) associated with mental retardation (MR) was examined to identify PITX3 mutations." (PMID 20376326, 2010). "In addition, mutations in transcription factor PITX3 have been identified in anterior segment dysgenesis and congenital cataracts." (PMID 26489929, 2016). "Mutations in the related gene Pitx3 are known to cause congenital cataracts." (PMID 21896182, 2011). "There were no pathological mutations in known genes associated with non-syndromic congenital cataracts, like CRYB, CRYG, Cx43, Cx46, Cx50, MIP, PITX3, MAF, HSF4, and so on." (PMID 28076398, 2017). "Most genes are associated with isolated congenital cataracts while mutations in the transcription factor genes PAX6, FOXE3, EYA1, MAF, and PITX3 lead to congenital cataract with ASD." (PMID 24555714, 2014). "Although several transcription factors such as Pax6, PITX3, HSF4, and HMX1 were allelic with congenital cataracts, MAF family genes are well characterized for the indispensable transcription factor regulating lens development." (PMID 27631609, 2016).